HDAC2 (histone deacetylase 2)
Diseases named in the same sentence as HDAC2 in open-access papers (continued):
Sharing a sentence is not in itself a finding about the gene and the disease.
tumor (continued). "Of note, the UCSC predicted that HDAC2 was a potential transcriptional regulator of PLIN1, an identified tumor suppressor in BC progression." (PMID 32110804, 2020). "p16, HDAC2 and RAD23 Homolog B, Nucleotide Excision Repair Protein (HR23B) tumour immunohistochemistry were evaluated." (PMID 33574900, 2020). "We report the mechanism by which HDAC2 regulates the expression of ISGs in tumor cells, and NOS1 induces epigenetic changes through S-nitrosylation of HDAC2, thereby leading to dysfunctional IFN signaling and promoting lung metastasis." (PMID 31805977, 2019). "The immunoblot analyses confirmed in P3 tumours the up‐regulation of OPN and SERPINA 1, whereas the expression of HDAC2, SRSF3 (spliceosome) and RPS27L (ribosome) was down‐regulated in this type of tumours." (PMID 31560832, 2019). "Here we present in silico, in vitro, and mouse xenograft studies that suggest that specifically targeting HDAC2 reduces MDM2 expression and has anti-tumor affects in DDLPS." (PMID 31620242, 2019). "HDAC1 and HDAC2, two components of the NURD complex, are highly expressed in tumor patients with bad prognosis." (PMID 30310855, 2018). "These scenarios fit well with our working model that TRPS1 recruits USP4 to stabilize HDAC2 and represses expression of AES, Casp7, PERP, and ZW10 to confer tumor growth." (PMID 30071870, 2018). "Significantly, our results revealed the scaffolding function of TPRS1 in USP4-directed HDAC2 de-ubiquitination and provided new mechanistic insights into the crosstalk between TRPS1, ubiquitin, and histone modification systems leading to tumor growth." (PMID 30071870, 2018). "Future studies will involve assessing KLF4 protein expression in mice tumors as well as the expression of HDAC2, HDAC3 and hTERT in the tumor tissues." (PMID 29899271, 2018). "Our working model suggests that TRPS1 recruits USP4 to stabilize HDAC2 repressing the expression of AES, Casp7, PERP, and ZW10 to confer tumor growth." (PMID 30071870, 2018). "The present study showed that tumor cell inoculation in tibia induced significantly increased expression of HDAC1 in the microglia and neurons in the SDH, with HDAC2 increased markedly in astrocytes." (PMID 29096654, 2017). "We found that the expression levels of CDK1, HDAC2 and RAD21 were increased in tumor tissues compared with the adjacent normal tissues." (PMID 28434945, 2017). "We selected HDAC2, HDAC3, and HDAC8 to further examine in 79 paraformaldehyde-fixed, paraffin-embedded paired CCA and adjacent non-tumor tissues with immunohistochemistry (IHC)." (PMID 27705912, 2016). "Among HDACs 1-10, class I HDACs (HDAC1, HDAC2, HDAC3, and HDAC8) and HDAC9 were more highly expressed in CCA tissues compared with paired non-tumor tissues (P<0.05)." (PMID 27705912, 2016). "HDAC protein expression was then assayed by Western blot (WB), and the expression of HDAC2, HDAC3, and HDAC8 were higher in CCA tissues compared with paired non-tumor tissues (P<0.05)." (PMID 27705912, 2016). "When the combined expression levels were analyzed, high expression of LSD1, HDAC2 and SIRT1 showed shorter patient survival time and shorter time to tumor relapse and correlated with poor tumor differentiation and a high level of tumor cell proliferation." (PMID 25139823, 2014). "The median percentages of positive tumor nuclei, used for the statistical analyses, were 85% for LSD1, 80% for HDAC2 and 70% for SIRT1." (PMID 25139823, 2014). "In summary, there are correlations between the combined expression levels of LSD1, HDAC2 and SIRT1 and tumor differentiation and between the combined expression levels of these enzymes and tumor cell proliferation." (PMID 25139823, 2014). "Percentages of positive nuclei for LSD1, HDAC2 and SIRT1 in the tumor and normal tissue cores were determined by IHC." (PMID 25139823, 2014).
tumor (continued). "A low differentiation grade was found in 21% of patients with low expression of LSD1, HDAC2 and SIRT1 and 43% of the patients with high expression of all three enzymes had a low grade of tumor differentiation." (PMID 25139823, 2014). "Our data reveal a crucial function of HDAC1/HDAC2 in the control of lineage specificity and a novel role of HDAC1 as a tumour suppressor in the epidermis." (PMID 24240174, 2013). "HDAC2 and HDAC3 are strongly expressed in subgroups of tumor with features of a more aggressive tumor type." (PMID 23627572, 2013). "Transcription of the cell cycle regulator p21 is directly regulated by HDAC1 and HDAC2 and is re-activated by HDAC inhibitors in tumor cells." (PMID 21615950, 2011). "Thus, to identify the molecular signature that may affect tumor cell growth, we employed and performed large-scale gene expression analysis on HDAC2 knockdown cells (Hep3B-shHDAC2) and compared with its corresponding control (Hep3B-mock) by using whole genome expression microarray." (PMID 22132221, 2011). "In previous studies, we have shown that the change in histone acetylation correlates with baseline expression of HDAC2 in PBMC and tumour cells." (PMID 21559012, 2011). "Conversely, the expression of HDAC1 and HDAC2 increases with tumor progression and recurrence, with no significant changes in other antigens based on tumor grade." (PMID 40940748, 2025). "To investigate the potential impact of IHCH9033 treatment on AML patients, we executed comparable gene expression analysis of these class I HDAC members between AML tumor and normal tissues, revealing that HDAC1, HDAC2 and HDAC3 were notably overexpressed in AML." (PMID 39955584, 2025). "HDAC2 knockdown represses transcription of glucose transporter 3 (GLUT3) by modulating microRNA-3189 (miR-3189) levels, thereby decreasing glucose uptake and inducing cell death as well as tumor suppression." (PMID 40450300, 2025). "HDAC1, HDAC2, and HDAC6-mediated deacetylation of Sp1 has been reported to enhance cell proliferation and stem cell maintenance, which may contribute to tumor progression and TMZ resistance." (PMID 40450300, 2025). "Moreover, HDAC2‐wt restored tumor proliferation suppressed by PJA2, and HDAC2‐mut promoted tumor growth and inhibited tumor apoptosis compared with HDAC2‐wt in PJA2 overexpressed cells." (PMID 39928532, 2025). "To explore TAGLN and HDAC2 expression in GBM patient surgical specimens, we performed IHC staining and observed that HDAC2 (which is a hypoxia‐related gene), TAGLN, CA9 (a hypoxic marker), and HIF1α were all located in GBM tumor cell nuclei and highly expressed in pseudopalisades (upper)." (PMID 38087889, 2024). "Exploring HDAC2 expression in primary tumours obtained from patients with and without liver metastasis revealed that HDAC2 was highly expressed in patients with liver metastasis compared to those without liver metastasis (p-value < 0.01)." (PMID 38255946, 2024). "Furthermore, HDAC2 and HDAC3 are strongly expressed in tumor subgroups with more aggressive features, such as less differentiated tumors and negative hormone receptor status." (PMID 38935814, 2024). "Interestingly, HDAC1, HDAC2, HDAC4, and HDAC11 showed a significant upregulation in tumor compared to normal liver tissue." (PMID 39529166, 2024). "Preliminary experiments did not yield differences in survival of tumor‐bearing mice and the lack of changes in HDAC2 and TAGLN expression among treatment groups as a pharmacodynamic study suggested that ineffective drug concentrations were achieved." (PMID 38087889, 2024). "In EC, upon MPA treatment, TRPS1 could act as a transcription corepressor and interact with HDAC2 to form a PR/TRPS1/HDAC2 complex to deacetylate RANKL, downregulating the expression of RANKL and thereby exerting an anti-tumor effect." (PMID 37344459, 2023).
tumor (continued). "Another study, conducted by Afroditi Nonni’s group, also examined the expression of HDAC2 in 118 deceased sporadic BC patients and its correlation with clinicopathological characteristics of the tumor and the prognosis of the patient." (PMID 37764768, 2023). "HDAC2 and 3 are frequently expressed at high levels in hormone-receptor negative tumours, while aberrant HDAC1 expression is common in hormone-receptor positive tumours." (PMID 35632748, 2022). "It revealed that upregulation of HDAC2 and PHOX2B promoted tumor weight." (PMID 35060363, 2022). "Nevertheless, most of these studies investigate HDAC-2 expression in BC cell lines or xenograft tumor models, but not patient-derived tumor samples." (PMID 36294811, 2022). "Class I HDACs and class III HDACs have tumor suppressor functions: conditional knockout mice for Hdac1 and Hdac2 develop lymphoid malignancies, as well as non-hematopoietic tumors." (PMID 35328416, 2022). "Surprisingly, there was a strong reduction in the tumor formation or no tumor growth in the mice injected HDAC2-KO cells." (PMID 34365463, 2021). "Furthermore, HDAC-1, HDAC-2 and HDAC-3 expression levels were positively correlated with tumor proliferative status, assessed as Ki67 labeling index." (PMID 34441281, 2021). "In our cohort, increased cytoplasmic HDAC-1 expression was indeed correlated with increased tumor size, whilst the correlation of HDAC-2 immunoreactivity with tumor size was not straightforward." (PMID 34638249, 2021). "It is particularly noteworthy that a PDX model using human clinical ESCC specimens substantiates our in vitro results showing that TRIB2 strongly induced radioresistance, while HDAC2 inhibition effectively blocked the effects of TRIB2 and strengthened the suppression of tumor growth by radiotherapy." (PMID 34586732, 2021). "This argues for a mixture of events explaining decreased tumor growth of HDAC1 and HDAC2 knockouts." (PMID 34654445, 2021). "HDAC2 IHC scores in tumours with liver metastasis were significantly higher than those in tumours without liver metastasis (P < 0.01) and normal tissues (P < 0.001), suggesting that HDAC2 accumulated in CRC patients, especially in ones with liver metastasis." (PMID 33325150, 2021). "According to the report, HDACs (HDAC1 and HDAC2) are necessary for the growth and survival of RCC tumor cells, and inhibition of HDACs might improve the response of oncologic chemotherapy for RCC." (PMID 33133154, 2020). "And PLIN1, a recently identified anti-tumor gene in BC was chosen to be research object since UCSC suggested that HDAC2 might be one of potential regulators of it." (PMID 32110804, 2020). "This HDAC2 inhibition reduces MDM2 expression and abrogates tumor growth in vitro and in vivo." (PMID 31620242, 2019). "Determination of the expression pattern of HDAC class I‐IV family members in the tumor (2102EP) and endothelial cells (Ea.hy926) used in this study revealed that the class I family members HDAC1, HDAC2, and HDAC3 are the primarily expressed HDACs in both cell lines." (PMID 31583820, 2019). "Because we found that HDAC2-MUT partially reversed the role of NOS1 in promoting lung metastasis, we further investigated whether HDAC2-MUT directly inhibited tumor growth." (PMID 31805977, 2019). "In many murine tumor models, HDAC1 and HDAC2 blockade inhibits tumor progress and CSC self-renewal." (PMID 30310855, 2018). "In addition, we found that 17-AAG had a combined effect in the downregulation of HDAC1, HDAC2, the anti-apoptotic gene BCL-2 and tumour survival gene STAT3 in Hep3B cells in combination with Resminostat." (PMID 30035186, 2018). "Our data provide a possible framework for tumour-relevant functions of HDAC1 and HDAC2." (PMID 29472538, 2018). "Taken together, our results indicate that Hdac1 and Hdac2 do not have a tumor suppressor function in B cells." (PMID 27886239, 2016).
tumor (continued). "As the relationship between survivin and HDAC2 has not been explored in the combinatorial treatment of CRC we investigated this in mice xenograft tumours." (PMID 27283986, 2016). "For staining of HDAC2 in tumor tissues, the kappa for scoring of the tumor tissue was not considered as substantial agreement." (PMID 25139823, 2014). "Finally, combined expression levels of the histone-modifying enzymes LSD1, HDAC2 and SIRT1 correlated with tumor differentiation and tumor cell proliferation." (PMID 25139823, 2014). "High expression of all three enzymes in tumor cells was correlated with reduced patient survival and shortened RFS compared to the expression level of the individual enzymes, implicating that LSD1, HDAC2 and SIRT1 act together in the same complex." (PMID 25139823, 2014). "HDAC2 expression did not significantly differ in tumor tissues compared to normal tissues (p = 0.4)." (PMID 25139823, 2014). "In addition, we investigated the relation between the combined expression levels of LSD1, HDAC2 and SIRT1 and tumor cell proliferation, assessed by ki-67 expression, which is another marker of aggressive tumors." (PMID 25139823, 2014). "Expression of LSD1 and SIRT1, but not of HDAC2, was significantly increased in tumor tissues compared to their normal counterparts (both p < 0.001)." (PMID 25139823, 2014). "HDAC2 and HDAC3 are strongly expressed in more aggressive tumor subtypes." (PMID 23627572, 2013). "Finally, using western blot we confirmed that HDAC1, HDAC2, HDAC3 and COX-2 are expressed in the BxPC-3 CAM tumor." (PMID 24040391, 2013). "More importantly, HDAC2 inhibitors not only inhibit nuclear PD-L1 translocation, enhancing the efficacy of PD-1/PD-L1 checkpoint inhibitors, but also significantly increase the proportion of CD8+ and CD8+GranB (granzyme B)+ cells within tumor-infiltrating lymphocytes." (PMID 40573881, 2025). "From the past studies, HDAC2 itself had a positive effect on M2 polarization, whereas HDAC4 and HDAC11 had the negative effects on M2 polarization, suggesting that increasing HDAC4 and HDAC11 expression and decreasing HDAC2 expression are targets for tumor immunotherapy." (PMID 40375990, 2025). "Through unknown mechanisms, heat shock protein 90 (USP90), histone deacetylase 2 (HDAC2), Cdk5 and Abl enzyme substrate 1 (CABLES1), the pituitary tumor apoptosis gene (PTAG), thrombospondin-1 (TSP-1), and caspase-8 (CASP-8) are also involved in the tumorigenesis of corticotrophinomas." (PMID 40299639, 2025). "Tumor cells were treated with STA, CCK8, colony formation, scratches, transwell and xenograft experiments showed that inhibition of HDAC2 by STA could weaken the malignant progression of NPC." (PMID 40050614, 2025). "This may suggest a strong positive relationship between HDAC7 and tumor infiltrating cells (TILs), especially considering CD4+ T cell populations whose levels generally correlate positively with HDAC7 expression and negatively with HDAC2 expression." (PMID 39063083, 2024). "However, HDAC2 overexpression has been observed in various B-cell lymphomas, where it directly contributes to the abnormal activation of BCL6, thereby promoting uncontrolled tumor growth." (PMID 39409979, 2024). "Tumor-free tissue sections were negative for HDAC-2 expression." (PMID 38201636, 2024). "Also, HDAC1, HDAC2, and HDAC3 play a regulatory role in restricting the transcription of STAT3 target genes within another commonly altered pathway, the JAK/STAT pathway, resulting in subsequent epigenetic silencing of tumor-suppressor genes." (PMID 39409979, 2024). "In previous studies, low CBX7 expression may be involved in promoting the tumor metastasis, in which CBX7 binds to the histone deacetylase 2 and inhibits its activity, leading to the histone deacetylation in the E-cad promoter and finally increasing the E-cad expression." (PMID 33748425, 2021).
tumor (continued). "The high-intensity staining in a large proportion of these tumor samples (71.4% for HDAC1 and 92.9% for HDAC2) suggests that HDACs are also relevant in the context of cisplatin-resistant phenotype, thus indicating that targeting with HDACis may be an effective therapy." (PMID 33050470, 2020). "Because of this epigenetic dysregulation involving overexpression of HDAC1, HDAC2, HDAC3, and LSD1, we anticipate that the 4SC-202, which specifically targets Class I HDACs (HDAC1, HDAC2, HDAC3, HDAC8) and LSD1, may selectively affect ATRT tumor cells." (PMID 32210076, 2020). "Whether NOS1 participates in the regulation of the IFNα response through S-nitrosylation of HDAC2 in tumor cells has not been determined." (PMID 31805977, 2019). "Interestingly, in contrast to previous observations in T cells, ablation of Hdac1 and/or Hdac2 in B cells did not lead to spontaneous tumor development." (PMID 27886239, 2016). "Indeed, we provide support for the notion that both HDACi and MTM promote neuroprotection by inhibiting the expression or functions of proteins that mediate transformation such as Myc, HDAC1, HDAC2 and HDAC3 and by promoting the expression of tumor suppressors such as p21waf1/cip1." (PMID 22582024, 2011). "Moreover, the vast majority of the cases with moderate/strong HDAC-2 nuclear IRS showed multiple clusters and widespread expression throughout the tumor (90%, 27/30), whereas only 16/44 (36%) of cases with absent/mild HDAC-2 IRS exhibited this pattern of staining (Fisher’s exact test, p < 0.0001)." (PMID 34638249, 2021). "Taken together, these results indicate that reduction of Hdac2 in absence of Hdac1 (Hdac1Δ/Δ; Hdac2Δ/+) impacts Eμ-myc tumorigenesis by reducing the Eμ-myc-induced blasts in the BM, resulting in reduced circulating tumor cells and eventually delays Eμ-myc tumorigenesis." (PMID 27886239, 2016). "Therefore, we hypothesize that the complex of LSD1, HDAC2 and SIRT1 has important roles, next to chromatin repression, in regulating cell survival and that aberrant expression of this complex leads to sustained survival of tumor cells." (PMID 25139823, 2014). "Thus, HDAC1 but not HDAC2 negatively controls tumour cell proliferation in the epidermis." (PMID 24240174, 2013). "Specifically, MYC showed positive correlations with oncogenic factors HDAC2, HDAC3, AKT2, and AKT3, while demonstrating negative correlations with tumor suppressors PTEN and FOXO1." (PMID 40229260, 2025). "More specifically, HDAC-2 and HDAC-3 proteins were correlated with a lower grade of tumor differentiation and negative estrogen receptor (ER) and progesterone receptor (PR) status." (PMID 34441281, 2021). "While HDAC2, HDAC3 and HDAC6 showed increased protein levels, the RNA levels either did not change (HDAC2 and HDAC3) or even decreased (HDAC6) in tumor samples." (PMID 23951168, 2013). "HDAC1 (P=0.006) and HDAC2 (P=0.047) expression but not HDAC3 (P=0.584) expression correlated positively with Gleason scores, with high-grade tumours expressing both isoforms at higher rates." (PMID 18212746, 2008). "Pharmacologic inhibition of HDAC2 with a selective HDAC2 inhibitor (santacruzamate A), but not of HDAC6, blocks PD-L1 nuclear translocation and induces the expression of immune-related genes involved in boosting anti-tumor immunity." (PMID 35070972, 2021). "On the other hand, tumour barrier functions of replicative stress and DNA damage signalling networks might be lost when HDAC1/HDAC2 are absent or inactivated." (PMID 29472538, 2018). "However, we did not observe any significant difference in HDAC2 and HDAC6 levels in tumor samples and adjacent normal controls." (PMID 26000099, 2015).